WNT5A (Wnt family member 5A)
Diseases named in the same sentence as WNT5A in open-access papers (continued):
Sharing a sentence is not in itself a finding about the gene and the disease.
tumor (continued). "A recent study shows that WNT5A regulates the expression of the tyrosine kinase receptors AXL and MER to promote tumor dormancy and drive dissemination." (PMID 36620565, 2022). "Conversely, WNT5A, WNT7B, WNT2, WNT7A, WNT10A and WNT3 were tumor-positive WNTs, which significantly increased in many carcinomas." (PMID 35850748, 2022). "Androgen-signaling inhibition elevated Wnt2, Wnt3a, and Wnt5a expression in CAF, and enhanced tumor epithelial cell survival." (PMID 35884514, 2022). "Especially, a panel of WNT components, including WNT5A, WNT7B, GPC1, and FZD6 or FZD7, shows tumor tissue-specific increment in CSCC, HNSC, LUSC, and BTCC." (PMID 35850748, 2022). "RYK knockdown in glioma cells suppressed matrix metalloproteinase-2 (MMP2) and Wnt5a-induced invasion, suggesting RYK can regulate extracellular matrix degradation and tumor invasive capacity." (PMID 35204808, 2022). "After identifying the relationship between WNT5A and SNAIL, we further detected SNAIL expression by performing an IHC analysis of a tissue array containing 145 paired tumor-normal samples." (PMID 35595735, 2022). "The results showed that CAFs in P-LNs were associated with the high expression of NFIB, IGLC2, IGHG4, C7, and CCL19, while CAFs in tumor 3 had high expression of DIO2, LGALS1, WNT5A, NEAT1, and MMP11 in the tumor." (PMID 36569924, 2022). "Consistent with the observed increase in WNT related genes in tumor cells, we saw high scores for WNT-related interactions (ligands Sfrp1 and Wnt5a and receptors Fzd6, Fzd7 and Lrp6) and significant BMP-related interactions (e.g. from Bmp4 with Bmpr1a)." (PMID 35600339, 2022). "Tumor cells need to switch from high-CTNNB1, low WNT5A to low-CTNNB1, high WNT5A to initiate metastasis and move away from the primary site." (PMID 36620565, 2022). "In particular, Wnt5a is frequently epigenetically inactivated in CRC, showing tumor-suppressive activity through counteraction of the canonical Wnt/beta-catenin signaling pathway and CRC metastasis." (PMID 33972671, 2021). "One recent meta-analysis concluded that Wnt5a expression was positively correlated with several clinicopathological parameters of GC, including LNM, tumor invasion depth, and advanced stages." (PMID 33654199, 2021). "This article analyzes publicly available gene and protein expression data and reveals the existence of a WNT5A/FZD2/FZD7/ROR2 signature, which correlates with tumor-infiltrating and mesenchymal cell marker expression." (PMID 33869179, 2021). "Since the expression levels of Wnt5a is increased in CRC cells, this ligand can progressively affect the different cellular processes of the tumor cells, including proliferation, differentiation, migration, and invasion." (PMID 34603445, 2021). "The increased FOSL2 in CAFs plays a pivotal role in promoting angiogenesis by regulating Wnt5a, thus stimulating activation of the downstream FZD5/NF-κB/ERK signaling axis in vascular endothelial cells to fuel tumor angiogenesis VEGF-independent patterns." (PMID 33754039, 2021). "As the oncogenesis of SFT/HPC is associated with angiogenesis, maintaining the mechanical stability of tumor vessels is more difficult in icSFT/HPCs than exSFT/HPCs due to the decreased expression of CLDN5 and WNT5A." (PMID 33799999, 2021). "We showed that the expression of WNT5A was low in icSFT/HPC and the level of CLDN5 protein, which constitutes a tight junction, was reduced in tumor vessels in icSFT/HPC." (PMID 33799999, 2021). "Expression of the canonical skeletal muscle WNT agonist Wnt5a (WNT5A), canonical WNT receptor Fzd1 (FZD1), and β‐catenin itself (CTNNB1) was all reduced with C‐26 tumor burden, whereas the negative regulator of β‐catenin, GSK3B, was up‐regulated." (PMID 31930715, 2020). "In line with previous reports 49, the expression of WNT5A was downregulated in HGSC in comparison to healthy ovarian tissue and in metastasis vs. primary tumor site (also confirmed on the protein level by WB)." (PMID 31903136, 2020).
tumor (continued). "Mechanistically, Wnt5a induced M2 polarization of TAMs by regulating CaMKII-ERK1/2-STAT3 pathway-mediated IL-10 secretion, thereby promoting tumor growth, invasion and metastasis of CRC." (PMID 32228612, 2020). "The authors have shown that Wnt5a supports TGF-β-mediated tumour suppressive functions by antagonising Wnt/β-catenin signalling and limiting tumour cell proliferation." (PMID 33080952, 2020). "In this study, we primarily found a novel TAM subtype, Wnt5a+ TAM, which played a vital role in tumor support." (PMID 32140070, 2020). "Our data not only report a novel Wnt5a+ TAM subtype and its pro-tumor roles in CRC, but also provide a novel insight into targeting Wnt5a in cancer therapy." (PMID 32140070, 2020). "Consistent with previous reports in PDAC organoids, WNT5A, WNT7A, WNT7B, and WNT10A mRNA were highly expressed in PDCLs, suggesting a tumor cell-intrinsic origin for these WNT ligands." (PMID 32402285, 2020). "Wnt5a induced M2 polarization of TAMs by regulating CaKMII-ERK1/2-STAT3 pathway-mediated IL-10 secretion, thereby enhancing tumor growth, invasion and metastasis of CRC." (PMID 32228612, 2020). "Taken together, these studies demonstrate the existence of a Wnt5a/ROR1–YAP/TAZ feedback loop that modulates the CSC phenotype, tumor progression, metastasis and, ultimately, drug resistance." (PMID 31382410, 2019). "In contrast to anti-tumor impacts of MSCs, various studies have shown that MSCs-secreted factors including, TWIST, MMP, WNT5A, and TGF-β stimulate tumor growth, progression, and metastasis." (PMID 32099602, 2019). "Wnt5a is involved in regulation of MMPs production via the activation of JNK and Src by tumor cells." (PMID 31698687, 2019). "Globally, these results indicate that increased expression of those EMT-related genes occurs along tumor progression, which is further underscored by the finding of increased CAMK2N1 and WNT5A immunoexpression in metastatic PCa." (PMID 31762801, 2019). "The effects of Wnt5a on other TLR4-expressing cells of various origin, such as tumor cells expressing TLR4, should however be investigated." (PMID 31098409, 2019). "Our findings provide a biological significance for the high levels of Wnt5a in patients with IPRES, which would contribute to the generation of a pro-inflammatory and immunosuppressive tumor microenvironment that precludes the effect of anti-PD-1 therapy." (PMID 31510045, 2019). "Among the 4 genes, ALDH1L1 and HOPX exhibited decreased inter-tumor variance of methylation levels after NAC treatment; meanwhile, WNT5A and SOX9 showed increased inter-tumor variance." (PMID 30774927, 2019). "All primary HRS cells specifically expressed TNFRSF8 (CD30) and most HRS and bystander cells expressed CD40, highlighting the quality of our data However, only a subset of tumours expressed LTR-driven TNFRSF11A and WNT5A transcripts." (PMID 30546079, 2019). "The result illustrated that BBR and knockdown of HNF4α suppressed tumor growth in vivo, and BBR decreased HNF4α, WNT5A and cytoplasmic β-catenin levels, the same effect as HNF4α knockout in vivo." (PMID 30405404, 2018). "In particular, introduction of AR mutation into the prostate epithelia of TRAMP mice resulted in enhanced tumor formation and growth as a consequence of stimulation of the non-canonical WNT signaling pathway, particularly through its ligand, WNT-5A." (PMID 29983878, 2018). "The IHC results showed a correlation between the expression of Wnt5a, Ror2 and CTHRC1 with high histological grade of the tumor, while E-cadherin showed an opposite trend of expression." (PMID 28427201, 2017). "We cover fundamental molecular players in the tumor microenvironment including extra- (CCL2, CSF-1, CXCL12, IL-4, IL-13, semaphorins, WNT5A, and WNT7B) and intracellular signals." (PMID 28197019, 2017).
tumor (continued). "On the other hand, miR-4510 treatment led to an increase in several important regulators of β-catenin functions and tumor suppressors such as AXIN2, E-cadherin (CDH1), LRP1 and WNT5A." (PMID 28476031, 2017). "The results indicated that higher expression of Wnt5a and ROR2 were found in ADC and SCC tissues than that in the matched, adjacent non-tumor tissues." (PMID 29054966, 2017). "It blocks ROR-dependent non canonical Wnt5a signaling through ROR-1 dephosphorylation, thus blocking tumor cell proliferation, migration and survival, leading to tumor cell death by apoptosis." (PMID 29387053, 2017). "Other ligands of the network include WNT2B, WNT5A, and WNT9A, differentially expressed by tumor cells and TAMs." (PMID 27215396, 2016). "Our data demonstrates that miR-374a functions as a tumor suppressor by directly reducing CCND1, in contrast with previous reports that miR-374a acts as oncogene by modulating tumor suppressors WIFI, PTEN and WNT5A." (PMID 27191497, 2016). "Finally, it may be possible in the future to use serum levels of Wnt5a, miR-27b, PPARgamma levels and/or activity of the tumor tissue as prognostic markers to identify groups of patients that are at higher risk of developing hemorrhage if treated with anti-angiogenic therapies." (PMID 27876017, 2016). "Early studies showed that in non–small-cell lung cancer (NSCLC), intra-tumoral Wnt5a overexpression was correlated with increased expression of β-catenin and VEGF-A in stromal cells, suggesting tumor-stromal cross-talk." (PMID 27571105, 2016). "Univariate analysis showed that cytoplasmic ROR2 expression, Wnt5a expression, tumor TNM stage, tumor status, lymph node metastasis, and combined ROR2 and Wnt5a expression level were correlated with overall survival of NSCLC patients." (PMID 26305508, 2015). "Silencing of FHL2, a β-catenin interacting protein, reduced WNT signaling in OS cells, the expression of WNT5A and WNT10B and tumor formation and lung metastasis in a mouse OS model." (PMID 25992885, 2015). "Relative expression of ROR2 and Wnt5a mRNA in NSCLC and matched tumor-adjacent tissues were quantified by quantitative reverse transcriptase polymerase chain reaction (qRT-PCR)." (PMID 26305508, 2015). "Therefore, the Wnt5a signaling cascade in cancer metastasis appears to be complex and may depend on binding receptors, downstream effectors, exogenous inhibitors and tumor microenvironments, as well as the extracellular matrix, particularly cell/tissue-tropic contexts." (PMID 24944588, 2014). "Firstly, we evaluated the relation between Wnt5a and MVD, which is a classic marker of tumor angiogenesis." (PMID 24999479, 2014). "Consistently, WNT5A inhibition by shRNA rescued PIAS1 knockdown-mediated suppression of mammosphere and tumor growth in vivo." (PMID 24586797, 2014). "This resulted in the up-regulation of EZH2-silenced tumor suppressor genes, including CDKN1C, DAB2IP, and WNT5a, in a dose-dependent manner in multiple cancer cell lines (e.g., T24, MBT2, and PC3)." (PMID 25431950, 2014). "The pathways that we have found to meet these criteria are induced by intrinsic genetic alterations, resulting in the downregulation of both the BIN-1 and TβRIII tumor suppressors and the upregulation of the pro-tumorigenic factors, COX2 and Wnt5a." (PMID 25339948, 2014). "Wnt5a, which is up-regulated in poorly differentiated and highly motile mesenchymal-like HCC cells, has been suggested to play a role in tumor progression by inducing epithelial mesenchymal transition." (PMID 24405831, 2014). "To address the role of Wnt5a as a tumor suppressor, we characterized tumor formation and progression in MMTV-Wnt1 and MMTV-Wnt1;MMTV-Wnt5a double transgenic mice by assessing tumor incidence, latency, and growth." (PMID 25401739, 2014). "However, the statistical association between Wnt5a expression and tumor histology could not be found in the limited sample size." (PMID 23349696, 2013).
tumor (continued). "The region located between 3p21.3 and 3p14.3, deleted in both cell sub-lines, contains several established tumor suppressor genes including LTF, TDGF1, WNT5a, and RASSF, as well as candidate tumor suppressors such as CACNA2D3, GNAI2, and SEMA3B." (PMID 23951555, 2013). "Indeed, in this study, we found that exogenous Wnt5a could enhance the phosphorylation of AKT and CREB, the expression of CREB-target genes, and the growth of tumor cells that expressed low-levels of Wnt5a, indicating that Wnt5a could act in a paracrine manner for such tumors." (PMID 22403610, 2012). "Our finding that ectopic expression of PRDM5 leads to the inhibition of WNT/β-catenin signaling in tumor cells, probably through upregulating DKK1, DKK2, and WNT5A, suggests a novel mechanistic link between PRDM5 and WNT signaling in human tumorigenesis." (PMID 22087297, 2011). "In CRC, DNA methylation has a vital role in defining prognostic subtypes, and aberrant Wnt signalling is critical for carcinogenesis; however, the prevalence of Wnt5a methylation in CRC and its distribution among tumour subtypes is poorly understood." (PMID 21587258, 2011). "Interestingly, patients with high Wnt5a protein expression had a statistically significant more favorable outcome compared to patients with low Wnt5a protein expression indicating that the Wnt5a protein has a tumor suppressive function in the context of localized PCa." (PMID 22039506, 2011). "Wnt/β-catenin signalling was measured in tumours with altered TGF-β (dominant-negative TGF-β type II receptor, DNIIR) or Wnt5a (Wnt5a-/-) signalling as the accumulation of nuclear β-catenin using both confocal microscopy and cell fractionation." (PMID 19344510, 2009). "OPG and WNT5A appeared to possess no paracrine potency in mediating tumor cell drug sensitivity under any of the tested conditions." (PMID 40524253, 2025). "We found that Wnt5a expression was significantly correlated with the pT factor, metastasis, and a poor prognosis, independent of mucin phenotype or tumor location." (PMID 41008809, 2025). "Recent research reveals that WNT ligands, especially WNT5a, are primarily found in TAMs rather than within cancer cells, highlighting their indirect influence on tumor progression via macrophage-driven processes." (PMID 41041337, 2025). "Conversely, Wnt5a signals through non-canonical pathways and has been reported to exert both pro- and anti-tumour effects depending on cellular context; in PCa, it promotes migration and invasion via kinases such as Jnk." (PMID 41007281, 2025). "Notably, well-known tumor suppressors such as phosphatase and tensin homolog (PTEN) and Wingless-type family member 5A (WNT5A) have been identified as novel bona fide Hrd1 substrates in HCC cells." (PMID 39838427, 2025). "Comparative analysis of WNT pathways in primary LUAD and LUSC tumour tissues revealed increased mRNA levels of the noncanonical WNT5A in LUSC." (PMID 40223089, 2025). "WNT5A, an activator of noncanonical Wnt pathways, has protumorigenic functions and contributes to inflammation and immunosuppression in the tumor microenvironment." (PMID 40524253, 2025). "This could be explained by the ability of Wnt5A to suppress EMT and inhibit canonical Wnt signaling, which makes it a context-dependent tumor suppressor." (PMID 40943055, 2025). "After exposing WNT5a‐negative tumor vesicles to high concentrations of recombinant WNT5a, a significant portion of the protein attached to distinct EV fractions, with some remaining in the supernatant, indicating weaker, non‐specific binding." (PMID 40165582, 2025). "Moreover, this anti-tumor action observed in the PTSO groups of mice was corroborated molecularly by a reduction in cancer cell proliferation markers, specifically KI67 and WNT5A, which is a key marker of the Wnt/β-catenin signaling pathway." (PMID 41010517, 2025). "WNT5A induces CRPC via CCL2 and tumor-infiltrating macrophages." (PMID 38887275, 2024).
tumor (continued). "WNT5a is an oncogene that promotes the EMT and metastasis of tumor cells." (PMID 39440046, 2024). "On the other hand, the interaction between Wnt5a/ROR1 signaling and YAP/TAZ pathway may enhance cell proliferation and tumor development." (PMID 39551787, 2024). "However, they significantly differed in terms of marker genes (AKR1C1, FOSL1, LIF, and THAP2 vs. WNT5A, GREM1, TNC, and MMP1), tissue origins (normal vs. tumor), and organ preferences." (PMID 38744958, 2024). "Recent research shows that the Wnt5a non-canonical ligand can act as both a tumor suppressor and an oncogenic agent, promoting and inhibiting tumor processes through canonical and non-canonical Wnt signaling." (PMID 39200196, 2024). "They found that under conditions of reduced LRP5/LRP6, Wnt5a strongly activates the non-canonical pathway, leading to elevated p-c-jun and promoting tumor cell metastasis." (PMID 38706907, 2024). "The role of WNT5A in different cancer types is complex and not fully understood, with evidence of both tumor-suppressing and tumor-promoting effects." (PMID 39176352, 2024). "WNT5A methylation and expression was interrogated in the TCGA‐PRAD tumours (n = 492)." (PMID 39164966, 2024). "Recent findings suggest that WNT5a released from melanoma cells prompts paracrine WNT5-β-catenin signalling in DCs, resulting in an upsurge of the immunoregulatory enzyme indoleamine 2,3-dioxygenase-1 (IDO), which is pivotal in tumour-induced immune tolerance." (PMID 38136392, 2023). "Cancer cells secrete non-canonical wingless-related integration site 5a (Wnt5a), a homolog of the wingless protein in Drosophila species, which has tumor-promoting effects in melanoma, pancreatic cancer, and non-small cell lung cancer." (PMID 37817484, 2023). "A comparison of WNT5A and LGR5 protein expression in morphologically normal and cancer tissue patients revealed that normal tissue has a significantly higher WNT5A IRS than tumor tissue." (PMID 37998393, 2023). "TCAF2 is highly expressed in tumor pericytes (TPCs) derived from patients with colorectal cancer liver metastasis (CRCLM), which induces the secretion of Wnt5a through inhibiting TRPM8 channel and activates the STAT3 phosphorylation in tumor cells, thus facilitating CRCLM." (PMID 37635201, 2023). "Knocking-out Wnt5a but not Wnt10a in tumors suppressed the ability of tumor cells to induce Lin28b expression in CAFs, highlighting the role of Wnt5a in Lin28b induction." (PMID 37898598, 2023). "WNT5A, like DAPK1, is a tumor suppressor which can also modulate T cell activation." (PMID 38129593, 2023). "Studies have reported that FOSL2 can interact with Smad3, Wnt5a, or SNAI2 to promote tumour growth." (PMID 37380804, 2023). "Using IHC score in individual LUSC tumor tissue as a reference, we found that the expression profiling of WNT7B, WNT5A, FZD7 and GPC1 could be divided into four sub-clusters." (PMID 35850748, 2022). "Wnt signaling, mainly by WNT5A, and SPARC enhanced this barrier and facilitated tumor progression." (PMID 36452484, 2022). "As an important regulator of cell growth and differentiation, WNT5A has also been demonstrated to participate in the tumor growth inhibition through the non-canonical WNT/calcium signaling pathway." (PMID 35957916, 2022). "Wnt5A is mainly a non-canonical Wnt molecule that can act in various cancers as either a tumor-promoter or a tumor suppressor." (PMID 35053353, 2022). "Besides, the expressions of CXCL12-CXCR4, EGFR-MIF, FGFR1-FGR7, MIF-TNFRSF14, and WNT5A-PTPRK were predicted in the cross-talk between CAFs and tumor cells." (PMID 35784460, 2022). "Consequently, the pathway is like a bridge to connect tumor and TAMs, and TAMs have been proved to be involved in many pathways important to CRC,namely, NFKB1 pathway, STAT3 pathway, WNT5A pathway, and PI3K pathway." (PMID 35186730, 2022).